TRAP1 (TNF receptor associated protein 1)
Diseases named in the same sentence as TRAP1 in open-access papers (continued):
Sharing a sentence is not in itself a finding about the gene and the disease.
cancer (continued). "TRAP-1 is overexpressed in diverse types of cancers and was reported to accelerate prostate cancer development." (PMID 36344992, 2022). "A mechanistic insight that can explain the physiological consequences of metabolic rewiring by TRAP1, both from a cancer and non-cancer perspective, remains elusive." (PMID 35883436, 2022). "In our previous study, we have used machine learning to show that HSP90β and TRAP1 are aberrantly expressed in the urine of cancer patients and that the HSP90β, TRAP1 and co-chaperones can be used to identify cancer patients." (PMID 35572591, 2022). "Despite this controversy, much of the literature supports the idea that TRAP1 regulates metabolic transformation during tumorigenesis, TRAP1 is overexpressed in many cancers, and TRAP1 attenuation is detrimental to tumor cell survival." (PMID 35740911, 2022). "While this model is consistent with the reports highlighting the increased expression of TRAP1 in cancer, it is now clear that this molecule’s role in mitochondrial metabolism and function is likely more complex than originally predicted." (PMID 35883436, 2022). "In contrast, TRAP1 knock-down cells are more sensitive to deprivation of glutamine, the main energetic source alternative to glucose in cancer cells." (PMID 36510251, 2022). "These properties of the TRAP1 were implemented in a search for anti-cancer drugs, such as TRAP1 and Grp94 inhibitors." (PMID 35054835, 2022). "TRAP1 inhibitors also seem to selectively affect cancer cells and affect normal cells less, making them an attractive option." (PMID 34831420, 2021). "Here, it should be mentioned that tumor necrosis factor receptor-associated protein 1 (TRAP1), a member of the HSP90 subfamily, also contributes to adapting the cancer cell energy metabolism to hypoxic conditions." (PMID 33806538, 2021). "In fact, the role of TRAP1 and other Hsp90 chaperones in cancer is extensively studied and better understood than TRAP1 action in neurodegeneration." (PMID 34222342, 2021). "TRAP1 expression increases in both fish embryos and human cancer cells exposed to low oxygen tension." (PMID 33934112, 2021). "It seems that upregulation of TRAP1 triggers drug resistance of cancer cells and prevents apoptosis." (PMID 33921908, 2021). "TRAP1 expression is enhanced by hypoxic conditions both in developing embryos and in cancer models of Zebrafish and mammals." (PMID 33934112, 2021). "Because TRAP1 plays a role in shifting metabolism from towards glycolysis, levels of TRAP1 are often elevated in glycolytic cancers, and cancers that more often employ oxidative phosphorylation display lowered TRAP1 levels." (PMID 34831420, 2021). "TRAP1 has been reported to inhibit progression of numerous cancers, and we demonstrate that overexpression TRAP1 in CAFs reduces OXPHOS, proliferation and progression of OSCC in vivo and intro." (PMID 34906113, 2021). "As for TRAP1, this intramitochondrial chaperone has been characterized as a feasible target for future cancer treatments, while selective inhibitors of TRAP1 are presently developed and tested in cancer-related models." (PMID 33806538, 2021). "Highly selective small molecules targeting TRAP1 are needed to dissect the dynamics of client interaction under different conditions and thus the biochemical functions of this chaperone in cancer cells." (PMID 34888254, 2021). "Low levels of HSP90AB1/TRAP1, HSPA6/TRAP1, and HSP90AA1/TRAP1 in urine increase the probability of the patient having cancer, whereas low levels of CCT2/HSP90AB1 and HSPB1*HSPA9 in urine are strongly associated with non-cancer groups." (PMID 34692733, 2021). "TRAP1, another potential target of arzanol, regulates a metabolic switch between mitochondrial oxidative phosphorylation and glycolysis in cancer cells." (PMID 34059630, 2021). "S-nitrosylation of TRAP1 causes its degradation, destabilizing SDH and inducing apoptosis of cancer cells." (PMID 33925645, 2021).
cancer (continued). "Of note, the mitochondrial-localized TRAP1 inhibitor gamitrinib is currently being evaluated in a first-in-human phase I clinical trial for treatment of advanced cancers (ClinicalTrials.gov Identifier: NCT04827810)." (PMID 34132194, 2021). "In this review, we focused on different metabolic signatures in the context of cancer chemoresistance, paying special attention to the role of TRAP1 chaperone in cancer metabolic regulation." (PMID 31947673, 2020). "Functional analysis revealed that the upstream regulators (RICTOR, KDM5A, MAP4K4, and TRAP1) were activated due to the aberrant expression of sperm proteins in the cancer group compared to fertile men." (PMID 32942548, 2020). "The four Hsp90 subtypes (Hsp90α and Hsp90β in the cytoplasm and nucleus, the relative importance of GRP94 and TRAP1 in the endoplasmic reticulum in cancer) and mitochondria were still under research." (PMID 33537004, 2020). "On the other hand, the report of the crystal structure of TRAP1 has opened new scenarios regarding the possibility to selectively target this specific HSP90 paralog in cancer cells." (PMID 31947673, 2020). "Altogether, these pieces of evidence suggest that TRAP1 role in bioenergetics is cell‐ and context‐dependent and that cancer cells up/downregulate TRAP1 expression to adapt their bioenergetics to energy requirements and environmental conditions." (PMID 33025742, 2020). "p70S6K and glutamine endow TRAP1 knockdown cells with increased migratory potential, while TRAP1 enables cancer cells to migrate even under conditions of nutrient deprivation." (PMID 33575209, 2020). "Mitophagy can be regulated by different upstream regulators, such as PINK1, TRAP1, and Parkin, to induce cancer cell death." (PMID 32796618, 2020). "ERK1/2 binding and phosphorylation stimulate the formation of TRAP1/SDH multimeric complex and enhance the inhibitory activity of TRAP1 on SDH, thereby positively contributing to the TRAP1-induced metabolic reprogramming of cancer cells." (PMID 32411008, 2020). "TRAP1 expression is upregulated in various human malignancies, including nasopharyngeal, breast, and prostate cancers, as well as non-small cell lung cancer." (PMID 33575209, 2020). "TRAP1 represents a key determinant of cancer cell adaptation to different environmental conditions (i.e., oxidative, endoplasmic reticulum, and metabolic stress), being responsible for protection toward apoptosis, mitochondrial integrity, and drug resistance." (PMID 33065966, 2020). "Taken together, the data argue that the synergistic cytotoxic effects resulting from simultaneous inactivation of Hsp90, Grp94, and TRAP1 are due to impaired calcium homeostasis and disruption of Hsp90 client protein networks in cancer cells." (PMID 31956271, 2020). "Further analyses of the confocal fluorescence microscopy images revealed a significant positive correlation between TRAP1 expression and that of Hsp90 (r = 0.3301) and Grp94 (r = 0.6656) at a single cancer cell level." (PMID 31956271, 2020). "The mitochondrial HSP90 chaperone family member, TRAP1, is involved in several functions of cancer cells and, among others, regulation of cell bioenergetics." (PMID 33025742, 2020). "The TRAP1 has been initially characterized for its capacity to counteract oxidative stress and to protect cancer cells from ROS-mediated damage." (PMID 31947673, 2020). "In such a view, TRAP1 enhancement of Warburg metabolism is likely crucial in supplying cancer cells with metabolic substrates and energetic molecules to support biosynthetic processes and cell proliferation." (PMID 33025742, 2020). "In summary, the role of TRAP1 in different types of cancers is related to the disease state and prognosis of patients, suggesting that TRAP1 constitutes a target for tumor treatment." (PMID 33575209, 2020).
cancer (continued). "This ability to affect both cellular biosynthetic and bioenergetic processes makes TRAP1 an interesting protein in the context of tumor biology; however, its role in cancer is controversial." (PMID 31947673, 2020). "The TRAP1-mediated reprogramming of the work of mitochondria and energetic metabolism in cancer cells can play an especially important role within hypoxic (poorly vascularized) zones of solid tumors, sites where EMT is induced and CSC generation occurs." (PMID 32268506, 2020). "Recently, an increasing number of studies have shown that the mitochondrial chaperone TRAP1 functions as either an oncogene or a tumor suppressor in human malignant tumors and regulates tumor development." (PMID 33575209, 2020). "TRAP1 is significantly up-regulated in cancer cells and, therefore, targeting this molecule provides a “therapeutic window” in the treatment of malignant tumors." (PMID 31181660, 2019). "Although the differential expression of TRAP1 in cancer tissues plays an inhibitory role in mitochondrial apoptosis, knowledge of TRAP1 in normal tissues has not been well investigated." (PMID 31143823, 2019). "Other important candidates such as splicing factors PUF60 and XAB2 and TRAP1, a chaperone upregulated in various cancers and essential for maintaining mitochondrial homeostasis were downregulated in LSCs." (PMID 31448224, 2019). "In this scenario, TRAP1 acts as an oncogene or oncosuppressor gene depending on tumor type and cancer cells up/downregulate TRAP1 expression to adapt to unfavorable environments and remodel cell bioenergetics to fulfill high-energy demanding conditions." (PMID 31878280, 2019). "This last observation was also supported by the previous demonstration of increased TRAP1 expression in Letrozole-responsive cancers compared to Letrozole-insensitive cancers." (PMID 29621137, 2018). "TRAP1 is well studied in cancer since TRAP1 expression is tightly regulated in tumor cells, TRAP1 acts as a metabolic switch by targeting and inhibiting succinate dehydrogenase, which is important for metabolic re-purposing and inflammatory responses." (PMID 30072954, 2018). "The controversial expression data of TRAP1 in cancer suggested a potential dual role as an oncogene or onco-suppressor according to cancer type." (PMID 30158430, 2018). "Relevant in vitro studies formally demonstrated molecular mechanisms and pathways involved in TRAP1 control of cancer progression." (PMID 29621137, 2018). "A strict correlation between low TRAP1 expression and oxidative metabolism in OC cells is responsible for the progression of cancer and the response to platinum-based therapies through the activation of an inflammatory program." (PMID 29867465, 2018). "As far as we know, this is the first study to evaluate the relationship between TRAP1 expression and local cancer invasion." (PMID 28088229, 2017). "In the view of this finding, it seems reasonable to regard that TRAP1 expression contributes to local cancer invasion." (PMID 28088229, 2017). "The challenge for the future will be to carefully clarify the role of Trap1 in metastasis for different types of cancers both in tissue culture and in in vivo mouse models." (PMID 28407697, 2017). "The precise pathologic mechanisms for TRAP1 in promoting cancer invasion are still not fully understood and many questions remain to be answered." (PMID 28088229, 2017). "TRAP1 is responsible for several functions of cancer cells, i.e. protection from stress and apoptosis, drug resistance, protein homeostasis, maintenance of stemness, intracellular signaling, cell migration, cell cycle regulation, and bioenergetics." (PMID 28177905, 2017). "Although TRAP1 is overexpressed in disparate cancers, compared to normal tissues, bioinformatics studies reported here identified AML as a tumor type uniquely “addicted” to mitochondrial Hsp90s." (PMID 29348817, 2017).
cancer (continued). "TRAP1 is a driver of early stage cancer in vivo and the down-regulation of TRAP1 promises to be an “actionable” therapeutic target." (PMID 28881853, 2017). "Nevertheless, expression of TRAP1 in cancer cells is variable and in some cancers TRAP1 is even downregulated as compared to normal tissue counterparts." (PMID 26977249, 2016). "Based on the data of OC tissue biopsies, we analyzed TRAP1 levels in relation to cancer site: results show that low TRAP1 expression is mainly found in peritoneal biopsies localized at distant sites from the primary tumors." (PMID 27977010, 2016). "Because of its cell protective role and since both the mRNA and proteins levels of TRAP1 are highly expressed in certain cancer cell lines and tumors, TRAP1 has been proposed as an anticancer therapeutic target." (PMID 26977249, 2016). "We found that death induction was abrogated by CsA in cells with low TRAP1 levels (shTRAP1 cancer cells or mock MEFs)." (PMID 25564869, 2014). "The mitochondrial expression of Hsp90 and TRAP1 is often elevated in many cultured cancer cells and human cancer patients." (PMID 24927938, 2014). "TRAP1 protein levels were inversely correlated to PTP opening; indeed, knocking-down TRAP1 expression increased PTP sensitivity to Ca2+ in cancer cells, whereas TRAP1 overexpression inhibited pore opening in MEF cells." (PMID 25564869, 2014). "Gamitrinib treatment in combination with Thap did not sensitize astrocytes, possibly due to very low expression of both TRAP1 and Cyp-D in astrocytes compared to cancer cells." (PMID 24924916, 2014). "Consistent with pharmacological data, TRAP1 knockdown also sensitized cancer cells to Thap treatment." (PMID 24924916, 2014). "We observed that TTFA toxicity was markedly higher in cells with low TRAP1 levels (shTRAP1 cancer cells or mock MEFs), which were protected by NAC." (PMID 25564869, 2014). "Previous work has indicated that inhibition of Trap1 (along with mitochondrial Hsp90) is cytotoxic to cancer cells." (PMID 20552022, 2010). "The metabolic reprogramming of cancer cells from oxidative phosphorylation (OXPHOS) to glycolysis, a hallmark of tumor metastasis is partially regulated by TRAP1 through its interaction with succinate dehydrogenase alpha (SHDα) under hypoxic and nutrient deficient conditions." (PMID 41226319, 2025). "The establishment of this pseudo-hypoxic state by TRAP1 could act as a potent factor to amplify the pro-neoplastic functions of macrophages in the cancer microenvironment." (PMID 40877908, 2025). "We asked whether exposure to MPNST-CM in the presence of DMS could render TRAP1 KO Mφ/M2 macrophages capable of inducing motility of cancer cells, thus mimicking the effect of the conditioned medium on TRAP1 WT cells." (PMID 40877908, 2025). "As a result, TRAP1 boosts an aggressive pseudo-hypoxic phenotype, and its increased expression correlates with disease progression and poor prognosis in diverse cancer types, whereas TRAP1 genetic or pharmacological inhibition impedes the growth of various neoplastic models." (PMID 40074754, 2025). "In order to reveal TRAP1 point mutations and to provide indications on their effect on its activity, we first performed a bulk-tissue gene-expression analysis that revealed widespread but heterogeneous TRAP1 expression, both in normal tissues and in a variety of cancer types." (PMID 40074754, 2025). "The initial success of VM inhibition through TRAP1 suggests that, with careful selection, RBPs may be promising targets for disrupting VM and suppressing cancer progression." (PMID 40869298, 2025). "Thus, it can be envisioned that TRAP1 enables macrophages to install a pro-neoplastic transcriptional program orchestrated by HIF-1α independently of the hypoxic conditions found in the cancer regions furthest from blood vessels." (PMID 40877908, 2025).
cancer (continued). "Some studies have linked TRAP1 point mutations to various pathological conditions, but how these mutations affect chaperone functions is unknown, particularly in the context of cancer, where TRAP1 has been extensively studied." (PMID 40074754, 2025). "This information may provide a rationale for further studies aimed at investigating TRAP1 involvement in MB as additional process in the regulation of cancer bioenergetics in human CRC." (PMID 39210159, 2024). "Thus, cancer cells modulate the expression of TRAP1 and its protein network in response to hostile conditions and exploit several adaptive mechanisms, including the modulation of mitochondrial dynamics." (PMID 39210159, 2024). "TRAP1 is mitochondrial heat shock protein 75-kDa (Hsp75), belongs to the Hsp90 family and has been reported with the ability to offset oxidative stress in cancer cells, its overexpression reduces ROS production and protects cells from oxidative stress-mediated damage." (PMID 38933085, 2024). "In the era of personalized medicine, considering the recent design and development of novel TRAP1 inhibitors, this hypothesis is extremely intriguing in the perspective to candidate cancer cell metabolism pathways as targets for anticancer therapy." (PMID 39210159, 2024). "In conclusion, TRAP-1 potential for cancer-directed therapy is really high, although succinate’s responsibility on TRAP-1 protumoral involvement needs to be further analyzed and cleared, as it may be less relevant than other TRAP-1 targets." (PMID 37345199, 2023). "This study further provides the evidence that CVM-1125 binds to TRAP1, which may interfere the interaction of TRAP1 with CypD to negate its protective function, and subsequently induce mitochondrial apoptosis in cancer cells." (PMID 37351538, 2023). "Earlier, we reported TRAP-1 OE in metabolic alterations in cancer cells." (PMID 37165028, 2023). "TRAP1 is a Hsp90 homolog and the predominant chaperone in the mitochondria of cancer cells." (PMID 38098505, 2023). "Based on this, we propose TRAP-1-mediated metabolic rewiring in cancer." (PMID 37165028, 2023). "In this context, the hypothesis that inhibiting or reducing TRAP-1 activity may have beneficial effects over cancer seems promising." (PMID 37345199, 2023). "In addition, TRAP-1 is a Myc oncogene target, and its overexpression was detected in several tumor cells resistant to treatments, probably because it protects cancer cells from oxidative apoptosis through cyclophilin D (CypD) antagonism." (PMID 37345199, 2023). "TRAP1 has been regarded as a potential therapeutic target for cancer treatment." (PMID 37351538, 2023). "Also related to cancer metabolism, TRAP-1 promotes aerobic glycolysis by decreasing oxidative phosphorylation and enhances glutamine metabolism." (PMID 37345199, 2023). "Moreover, it has been suggested that TRAP-1-silenced cells lose their cancer-transforming potential, which can be further recovered with murine cDNA TRAP-1 transfection." (PMID 37345199, 2023). "Drugs inhibiting or antagonizing mitochondrial Hsp90 and its homolog TRAP1 may have great potential and specificity in treating cancer." (PMID 38098505, 2023). "synthesized a series of pyrazolo[3,4-d] pyrimidine derivatives, in which X-ray diffraction results showed that compounds 47 and 48 interacted with the ATP-binding pocket of TRAP1 protein, and they were shown to exhibit excellent anticancer efficacy in various cancer cells." (PMID 38098505, 2023). "TRAP1 performs different functions in different cancer cell types." (PMID 38098505, 2023). "These options should be investigated for TRAP-1 inhibitors, too, as this could open new avenues to improve the current available treatments for cancer patients." (PMID 37345199, 2023). "Studies from the field of cancer research have suggested that TRAP1 promotes cell survival." (PMID 35163711, 2022).